INS (insulin)
Diseases named in the same sentence as INS in open-access papers (continued):
Sharing a sentence is not in itself a finding about the gene and the disease.
prostate carcinoma (continued). "The main goal of this study was to evaluate the effect of preadipocyte and adipocyte secretome in the proliferation, migration and invasion of androgen independent prostate carcinoma cells (RM1) and to assess cell proliferation in the presence of the adiposity signals leptin and insulin." (PMID 25928422, 2015). "We recently published that dietary fat reduction combined with IGF-1R antibody blockade resulted in decreased proliferation in prostate cancer xenografts and a reduction in serum insulin and TNF alpha levels without affecting final tumor weights." (PMID 23823800, 2013). "The ability of AMPK to potentiate insulin action on cancer cell growth and survival has not been greatly explored in models of prostate cancer." (PMID 22548055, 2012). "Tseng also reported that insulin use is not significantly predictive for prostate cancer mortality in diabetic Taiwanese." (PMID 22719752, 2012). "Thus, all our findings predict increased proliferative effects of insulin and IGF-II in prostate cancer." (PMID 23251408, 2012). "Given that PTEN can be a major inhibitor of insulin/IGF signaling and is a known target of miR-25 in prostate cancer cells, miR-25 may target PTEN to increase insulin/IGF signaling and repress FoxO activity." (PMID 21386132, 2011). "Medications, specifically exogenous insulin, statins, and in the future, glucagon-like peptide 1 receptor agonists and sodium–glucose cotransporter 2 inhibitors, may modify the relationship between T2DM, glycemic control, and prostate cancer." (PMID 40693585, 2025). "We found that the insulin signaling pathway, PI3K/Akt signaling pathway, Hypoxia-inducible factor 1 (HIF-1) signaling pathway, FoxO signaling pathway, and cancer-related pathways such as prostate cancer were the potential fundamental mechanisms of C. sativa in the treatment of T2D." (PMID 37754241, 2023). "While the mechanism by which MR inhibits prostate cancer development is not known, evidence suggests that MR may work by inhibiting prostate cancer cell proliferation, inhibiting the insulin/IGF-1 axis, or by reducing polyamine synthesis." (PMID 32138282, 2020). "In this study, we initially sought to test a biologically derived hypothesis that baseline insulin levels with or without other markers would predict time to castration-resistant progression in patients with advanced prostate cancer treated with ADT." (PMID 27599544, 2016). "An association between INS/DEL and prostate cancer was not seen." (PMID 24800880, 2014). "In addition, it has been shown that insulin glargine, but not human insulin, increases resistance to apoptosis in several tumor cell lines including colorectal, breast, and prostate cancers." (PMID 21738645, 2011). "Insulin levels were also higher in prostate cancer patients with no physical activity which suggests that lifestyle modifications like dietary habits and physical exercise might improve insulin sensitivity that could further reduce the progression to advanced-stage prostate cancer." (PMID 39781138, 2024). "We created a map of the KEGG prostate cancer pathway (entry hsa05215) and identified controlled proteins, finding drugs that could potentially affect phosphatidylinositol 3-kinase (PI3K; insulin sensitivity), glycogen synthase kinase-3 (GSK3; glycogenesis), and AKT (insulin sensitivity)." (PMID 38034011, 2023). "In case of IR in prostate cancer patients, heterogeneous binding of insulin was inhibited on the platelet surface and that is why the level of insulin was found to be low and here DCN-2 might impart the major role in the reduction or impairment of insulin action in the condition." (PMID 31300527, 2019). "The role of insulin in the aetiology of prostate cancer is implicated by the observations from this and another study in China that increased risk of prostate cancer was associated with genetic variation in INS, but not its neighbouring genes, as well as elevated fasting insulin levels." (PMID 12610512, 2003).
prostate carcinoma (continued). "In the stratified Cox model, the metformin cohort had an aHR of 0.69 (95% CI = 0.49‐0.96, P = 0.0039) for prostate cancer, compared to the nonmetformin cohort after the adjustment of age, TCM for BPH use, TCM for DM use, insulin usage, and CCI." (PMID 30968600, 2019). "Oxandrolone is currently the agent of choice, unless contraindicated with the presence of prostate cancer, as this agent is safe, easy to administer, and does not have the metabolic side effects of HGH, IGF-1, and insulin." (PMID 16921407, 2005).
diabetic retinopathy (217 papers, 2007 to 2026). "Regarding specific event types, insulin degludec and insulin detemir were primarily associated with diabetic retinopathy, whereas insulin glargine showed the strongest association with diabetic glaucoma (ROR = 50.36)." (PMID 41924517, 2026). "A systematic review and meta‐analysis including 24 studies with 9302 patients found a relative risk of incident diabetic retinopathy of 0.45 with insulin pump therapy compared to MDI." (PMID 40390300, 2025). "Our study also demonstrates an increased relative risk of diabetic retinopathy for insulin pump users compared to MDI." (PMID 40390300, 2025). "Phospholipase D (PLD) signaling is implicated in glucose-induced insulin secretion and diabetic retinopathy." (PMID 41011980, 2025). "There was a significant association between the severity of diabetic retinopathy and the higher HbA1c levels, the use of insulin as a treatment modality, and the higher blood sugar levels in our study population." (PMID 39161485, 2024). "We found a significant association between the severity of diabetic retinopathy and the use of insulin as a treatment modality, i.e., a higher proportion of the severe forms of DR patients were on insulin than the milder forms of the DR." (PMID 39161485, 2024). "Diabetic retinopathy is a prognostic state that leads to the destruction of pancreatic B-cell function, which causes a decrease or absolute loss of insulin inside the body." (PMID 39495998, 2024). "When restricting the analysis to exclude patients on concomitant GLP-1RA, a lower risk of “diabetic retinopathy” vs. insulin persisted (ROR 0.12, 95% CI 0.06–0.22)." (PMID 39141075, 2024). "Compared with SGLT2i with insulin, GLP1-ra with insulin was associated with higher risk of diabetic retinopathy (1.205; 1.153, 1.259) and diabetic macular oedema (1.130; 1.056, 1.208)." (PMID 38584180, 2024). "Nonetheless, insulin therapy is deemed unsuccessful in controlling the incidence of diabetic retinopathy (DR) and is likely a risk factor." (PMID 34803500, 2021). "In the case of insulin-associated progression of diabetic retinopathy, it is more likely that retina endothelial activation plays a leading role, as our in vitro observation suggests no involvement of microglia activation." (PMID 34803500, 2021). "This is a possible mechanism by which insulin administration can cause neovascularization as found in diabetic retinopathy." (PMID 29017477, 2017). "Yet, this increase in diabetic retinopathy risk was also reversed after 2 years of intensive treatment with insulin." (PMID 29017477, 2017). "Insulin treatment has been associated with a paradoxical worsening of diabetes retinopathy since many years in European cohorts." (PMID 29017477, 2017). "Earlier studies suggested that insulin therapy may increase the risk of diabetic retinopathy, possibly due to rapid glucose lowering." (PMID 41011236, 2025). "It is possible that the relatively late start of insulin treatment and metabolic control explains the higher risk of diabetic retinopathy and polyneuropathy, initially manifested by reduced capillary density in the SCP or RPE dysfunction, and, as we show, reduced choriocapillary flow." (PMID 40164944, 2025). "Genetic factors associated with the development of diabetic retinopathy mutations or variations in genes involved in glucose and lipid metabolism, such as the gene for insulin (INS) or the transcription factor 7-like 2 (TCF7L2), have been associated with an increased risk of diabetic retinopathy." (PMID 38918766, 2024). "In summary, the integration of CGM and insulin pump therapy in the management of T1D not only improves glycemic control, but also has the potential to significantly reduce the risk of developing microangiopathic complications such as diabetic retinopathy." (PMID 38337523, 2024).
diabetic retinopathy (continued). "On this basis, it could be postulated that glucose-lowering agents with more capacity to mitigate glucose variability, such as current long-acting insulins or the next generation of ‘smart insulin’, could reduce the risk of diabetic retinopathy." (PMID 37277664, 2023). "This contradicting activity of insulin is yet to be scientifically understood due to the complex structure of the retina with multiple types of cells involved in the pathogenic development of diabetic retinopathy." (PMID 34803500, 2021). "Here we revisit evidence on the association between diabetic retinopathy and insulin use, and we propose a novel hypothesis to support this relationship." (PMID 29017477, 2017). "However, recent literature has clearly demonstrated an incremented risk of diabetic retinopathy with regard to insulin treatment." (PMID 29017477, 2017). "However, tight glycemic control with insulin is associated with recurrent hypoglycemic episodes, and the risk of early worsening of diabetic retinopathy." (PMID 29017477, 2017). "Additionally, epidemiological studies have shown that insulin therapy is an independent risk factor for the progression of intraocular neovascularization in diabetic retinopathy." (PMID 28424632, 2017). "Given the critical role of retinal capillary loss during diabetic retinopathy pathogenesis, these data provide evidence that rescuing insulin signalling may decrease retinal endothelial cell apoptosis, thus potentially improving diabetic retinopathy outcomes." (PMID 27514532, 2016). "Similarly, high serum total cholesterol, high serum LDL-cholesterol, presence of albuminuria and insulin therapy were found to have significant associations with the development of diabetic retinopathy as shown in Table-III." (PMID 24353572, 2013). "Nox4 may be an attractive therapeutic target for diabetic retinopathy caused by intensive insulin treatment." (PMID 23144758, 2012). "This suggests that the loss of the prosurvival insulin-signaling pathway may play a role in diabetic retinopathy." (PMID 21293735, 2011). "Research shows that insulin has neurotrophic properties and that the loss of its pro-survival pathways may have a role in diabetic retinopathy." (PMID 21293735, 2011). "Similarly the WESDR found a significant association between diabetic retinopathy and cholesterol level in insulin treated diabetic patients." (PMID 21346842, 2008). "This suggests that ppVD is similar to DCP-VD and reflects disease progression earlier than other indicators, suggesting that insulin intensification could cause microcirculation disorder of the optic disc area while early worsening of diabetic retinopathy (EWDR) progresses much earlier." (PMID 35459162, 2022). "Because others have reported that sodium salicylate is effective in reducing neuronal thickness and vascular changes associated with diabetic retinopathy in a type 1 rat model, we wanted to confirm whether salicylate also improved insulin signaling in a type 2 diabetic rat model." (PMID 25874611, 2015). "Furthermore, we hypothesize that this link may contribute to lesions similar to diabetic retinopathy in that the loss of adrenergic input observed in diabetic retinopathy may disrupt normal anti-apoptotic insulin signaling, leading to retinal cell death." (PMID 23894672, 2013). "Compared with the NDKD group, patients with DN were younger, had a longer duration of DM, more often required insulin therapy, more frequently demonstrated diabetic retinopathy (DR) and nephrotic syndrome, and exhibited higher HbA1c levels." (PMID 41598592, 2026). "The pathophysiology of diabetic retinopathy is complex and involves several key disorders, primarily related to disruptions in glucose homeostasis, insulin secretion, and action." (PMID 39802191, 2025). "Impaired insulin signaling contributes to diabetic retinopathy, retinitis pigmentosa, and age-related degeneration by disrupting energy homeostasis and trophic support." (PMID 41301488, 2025).
diabetic retinopathy (continued). "A more recent Scottish retrospective cohort study found a smaller proportion of adults had progression of diabetic retinopathy with insulin pumps compared to MDI therapy over 2.3 years of follow‐up." (PMID 40390300, 2025). "IL-1β, crucial in modulating insulin secretion and β-cell apoptosis, increases significantly with diabetic retinopathy severity." (PMID 41030257, 2025). "The HR for diabetic retinopathy was 1.308 (95% CI 1.261, 1.357; χ2=29.342), indicating a statistically higher risk of diabetic retinopathy in the GLP1-ra and insulin cohort compared with the control cohort." (PMID 38584180, 2024). "The HR for diabetic retinopathy was 1.205 (95% CI 1.153, 1.259; χ2=1.818), indicating a higher risk of diabetic retinopathy in the GLP1-ra and insulin cohort compared with the SGLT2i and insulin cohort." (PMID 38584180, 2024). "It was observed that more severe stages of diabetic retinopathy were seen in patients who were on treatment with insulin than in patients who were on treatment with OHA." (PMID 39161485, 2024). "Approximately 20.6%, 44.8%, and 14.0% of diabetic participants used insulin, oral hypoglycemic agents, and had diabetic retinopathy, respectively." (PMID 39061109, 2024). "In brief, E-values for SGLT2i + insulin vs control and GLP1-ra + insulin vs control analyses were generally greater than 1.5 (except for the diabetic retinopathy outcome in the SGLT2i + insulin vs control analysis which was 1.36)." (PMID 38584180, 2024). "Evidences that glycemic and insulin levels have an effect on eye microcirculation come from studies on diabetic patients and in particular from the diabetic retinopathy." (PMID 38963584, 2024). "Specifically, miR-125a-5p promotes insulin sensitivity and enhances β cell function in the pancreas while also playing a role in regulating related factors in diabetic retinopathy." (PMID 39595174, 2024). "In men, there was a negative correlation with age, history of disease, diabetic neuropathy, diabetic retinopathy, insulin use, and PWV, and a positive correlation with BMI." (PMID 39693147, 2024). "A comparative analysis showed favourable outcomes with SGLT2i and insulin in the development of diabetic macular oedema and diabetic retinopathy." (PMID 38584180, 2024). "With respect to insulin, TZP was associated with a lower risk of “diabetic retinopathy” (ROR 0.14, 95% CI 0.08–0.24) and a greater risk of “medullary thyroid cancer” (ROR 2.88, 95% CI 1.37–1.82)." (PMID 39141075, 2024). "Multinominal logistic regression showed that insulin treatment increases the chance diabetic retinopathy 8.5-folds (P = 0.003) in comparison to oral medication." (PMID 37828117, 2023). "In this study we showed that we showed that the chance of developing diabetic retinopathy in people receiving the PIns was fourfolds more than oral treatment group, but it was about sixfolds in insulin group." (PMID 37828117, 2023). "The patient was diagnosed with slight diabetic retinopathy and peripheral neuropathy and was initially prescribed low-dose insulin and metformin." (PMID 37711893, 2023). "Among these, early onset at a younger age, longer disease duration, and insulin usage demonstrated the strongest predictive capability for diabetic retinopathy." (PMID 37779807, 2023). "In this study, we showed that in diabetic patients who had received insulin the chance of diabetic retinopathy was about sixfolds in comparison to oral medication group." (PMID 37828117, 2023). "Some key pathways such as TGF-beta signaling, MAPK signaling, JAK-STAT signaling, VEGF signaling, citrate cycle (TCA cycle), and insulin signaling pathways have been indexed from the KEGG disease database to be closely related to diabetic retinopathy." (PMID 35154512, 2022). "She (II-1) had diabetic retinopathy and diabetic neuropathy and was previously prescribed acarbose and insulin." (PMID 35992135, 2022). "The relevance of insulin doses and diabetic retinopathy had been well demonstrated in previous studies." (PMID 35459162, 2022).